TLR4 (toll like receptor 4)
Description:
Transmembrane receptor that functions as a pattern recognition receptor recognizing pathogen- and damage-associated molecular patterns (PAMPs and DAMPs) to induce innate immune responses via downstream signaling pathways. At the plasma membrane, cooperates with LY96 to mediate the innate immune response to bacterial lipopolysaccharide (LPS). Also involved in LPS-independent inflammatory responses triggered by free fatty acids, such as palmitate, and Ni(2+). Mechanistically, acts via MYD88, TIRAP and TRAF6, leading to NF-kappa-B activation, cytokine secretion and the inflammatory response. Alternatively, CD14-mediated TLR4 internalization via endocytosis is associated with the initiation of a MYD88-independent signaling via the TICAM1-TBK1-IRF3 axis leading to type I interferon production. In addition to the secretion of proinflammatory cytokines, initiates the activation of NLRP3 inflammasome and formation of a positive feedback loop between autophagy and NF-kappa-B signaling cascade. In complex with TLR6, promotes inflammation in monocytes/macrophages by associating with TLR6 and the receptor CD86. Upon ligand binding, such as oxLDL or amyloid-beta 42, the TLR4:TLR6 complex is internalized and triggers inflammatory response, leading to NF-kappa-B-dependent production of CXCL1, CXCL2 and CCL9 cytokines, via MYD88 signaling pathway, and CCL5 cytokine, via TICAM1 signaling pathway. In myeloid dendritic cells, vesicular stomatitis virus glycoprotein G but not LPS promotes the activation of IRF7, leading to type I IFN production in a CD14-dependent manner. Required for the migration-promoting effects of ZG16B/PAUF on pancreatic cancer cells.
Synonyms: CD284; hToll; TLR-4; ARMD10; TOLL
Tractability: Small molecule: a drug acting on it is in phase 2 or 3 trials; a structure with a bound ligand is known; a high-quality ligand is known; it belongs to a druggable protein family. Antibody: UniProt places it where antibodies can reach, with high confidence; its Gene Ontology location is reachable by antibodies, with high confidence; UniProt predicts a signal peptide or a membrane-spanning region. PROTAC: UniProt records ubiquitination sites on it; its protein half-life has been measured; a small molecule that binds it is known.
Target class: Toll-like and Il-1 receptors; Membrane receptor
Chemical probes: ML021
Safety:
Unwanted effects reported when the protein is acted on. In parentheses: how it was acted on, where the effect was seen, and who reports it.
adverse drug events (source: ClinPGx)
Gene: Protein-coding gene on chromosome 9 (117,704,175 to 117,724,735, forward strand). Ensembl gene ENSG00000136869.
Subcellular location: Cell membrane; Early endosome; Cell projection, ruffle
Subcellular location (Human Protein Atlas): Golgi apparatus; Plasma membrane
Pathways (Reactome):
Immune System: Activation of IRF3, IRF7 mediated by TBK1, IKKε (IKBKE); ER-Phagosome pathway; IKK complex recruitment mediated by RIP1; IRAK2 mediated activation of TAK1 complex upon TLR7/8 or 9 stimulation; MyD88-independent TLR4 cascade; MyD88:MAL(TIRAP) cascade initiated on plasma membrane; Regulation of TBK1, IKKε (IKBKE)-mediated activation of IRF3, IRF7; Regulation of TLR by endogenous ligand; TRAF6-mediated induction of TAK1 complex within TLR4 complex; TRIF-mediated programmed cell death; Toll Like Receptor 4 (TLR4) Cascade
Disease: Dengue Virus-Host Interactions; IRAK4 deficiency (TLR2/4); MyD88 deficiency (TLR2/4); RSV-host interactions; Respiratory syncytial virus (RSV) attachment and entry
Cellular responses to stimuli: Heme signaling
Programmed Cell Death: Caspase activation via Death Receptors in the presence of ligand
Gene Ontology:
Molecular function: identical protein binding; lipopolysaccharide binding; lipopolysaccharide immune receptor activity; protein binding; protein heterodimerization activity; signaling receptor activity; signaling receptor binding; transmembrane signaling receptor activity; amyloid-beta binding
Biological process: cellular response to amyloid-beta; cellular response to lipopolysaccharide; cellular response to mechanical stimulus; cellular response to oxidised low-density lipoprotein particle stimulus; cellular response to type II interferon; defense response to bacterium; detection of lipopolysaccharide; inflammatory response; lipopolysaccharide-mediated signaling pathway; macrophage activation; MyD88-dependent toll-like receptor signaling pathway; phagocytosis; positive regulation of canonical NF-kappaB signal transduction; positive regulation of cellular response to macrophage colony-stimulating factor stimulus; positive regulation of chemokine (C-X-C motif) ligand 2 production; positive regulation of chemokine production; positive regulation of cytokine production involved in inflammatory response; positive regulation of gene expression; positive regulation of inflammatory response; positive regulation of interleukin-1 beta production; positive regulation of interleukin-12 production; positive regulation of interleukin-6 production; positive regulation of interleukin-8 production; positive regulation of matrix metallopeptidase secretion; positive regulation of transcription by RNA polymerase II; and 37 more
Cellular component: cell surface; cytoplasm; endosome membrane; external side of plasma membrane; lipopolysaccharide receptor complex; perinuclear region of cytoplasm; phagocytic cup; plasma membrane; receptor complex; early endosome; membrane; ruffle
Genetic constraint (gnomAD): Loss-of-function variants: 19 observed, 32.5 expected, observed/expected ratio (o/e) 0.58, 90% interval 0.41 to 0.86. The upper end of that interval is the gene's LOEUF score, 0.86, which puts it in group 3 of 6, group 1 being the genes least tolerant of losing a copy. Missense variants: 926 observed, 1,014 expected, observed/expected ratio (o/e) 0.91, 90% interval 0.86 to 0.96. Synonymous variants: 363 observed, 387.47 expected, observed/expected ratio (o/e) 0.94, 90% interval 0.86 to 1.02.
Homologues: Orthologues: chimpanzee TLR4 (99% identical), macaque TLR4 (93% identical), pig TLR4 (73% identical), rabbit TLR4 (73% identical), guinea pig TLR4 (72% identical), mouse Tlr4 (67% identical), rat Tlr4 (67% identical), dog TLR4 (57% identical). Paralogues in human: TLR5 (21% identical), TLR7 (21% identical), TLR2 (20% identical), TLR8 (20% identical), TLR3 (19% identical), TLR6 (18% identical), TLR1 (18% identical), TLR10 (18% identical), CD180 (16% identical), LRRC32 (15% identical), IGFALS (13% identical), NRROS (13% identical), and 10 more.
Diseases named in the same sentence as TLR4 in open-access papers:
TLR4 is named in the same sentence as 1,101 diseases in open-access papers, as found by Europe PMC text mining. Sharing a sentence is not in itself a finding about the gene and the disease. The quoted sentences say what the papers report.
Sepsis (971 papers, 2007 to 2026). Sepsis is defined as life-threatening organ dysfunction caused by a dysregulated host response to infection. "Several single-nucleotide polymorphisms (SNPs) in TLR2 and TLR4 have been identified in children and adult patients presenting with sepsis and admitted to intensive care units." (PMID 41598258, 2026). "Studies have suggested that TLR4, associated with its downstream molecule MyD88, plays an important role in inflammation during sepsis." (PMID 40148079, 2025). "Another TLR4 antagonist E5564 is associated with lower mortality in severe sepsis patients in phase II clinical trials." (PMID 40379629, 2025). "TLR4, a key regulator in various physiological and pathological processes, including liver disease, has been implicated in sepsis-related liver injury." (PMID 39067063, 2025). "Sepsis, another inflammation-associated condition, is triggered when lipopolysaccharide binds to TLR4, initiating the production of large quantities of inflammatory cytokines, which play a pivotal role in the onset of sepsis." (PMID 40051564, 2025). "For example, one study used time-dependent multi-omics integration to reveal the role of the TLR4 pathway in sepsis-associated liver dysfunction models, surpassing limitations of single omics analysis and uncovering potential sepsis pathological mechanisms." (PMID 41300910, 2025). "These analyses together with reported literatures 33 indeed confirmed the TLR2 and TLR4 up-regulation as a strong pathogenic factor in sepsis patients." (PMID 40963927, 2025). "This TREM1- NF-κB interaction represents a mechanism distinct from the parallel activation of TREM1 and TLR4 signaling observed in sepsis 38, suggesting a TBI-specific damage-associated molecular patterns co-recognition mechanism." (PMID 40963908, 2025). "Regarding genetic polymorphisms, some evidence pertains to TLR4 variants (Asp299Gly, Thr399Ile) in sepsis." (PMID 41154281, 2025). "Computer modelling using available data on the responses of TLR4, NF-κB, and heart rate to sepsis, also predicted an increase and loss of circadian rhythm of plasma epinephrine and norepinephrine in endotoxemia-induced sepsis in humans." (PMID 39968295, 2025). "Collectively, ginsenosides Rg1, Rb1, and Rk1 confer multi-faceted renoprotection against sepsis-induced acute kidney injury through multiple mechanisms, including TLR4, NF-κB, NLRP3, STAT1/3, and ferroptosis-associated pathways." (PMID 41415561, 2025). "It regulates TLR4 endocytosis and stimulates the secretion of inflammatory cytokines associated with sepsis." (PMID 38731999, 2024). "In summary, within a cohort of AML patients following induction chemotherapy, it was observed that polymorphisms of TLR2 and TLR4 influence the risk of developing sepsis and pneumonia." (PMID 38982248, 2024). "TLR4, a key player in initiating the innate immune response, is implicated in the inflammatory surge seen in sepsis." (PMID 38546748, 2024). "It has been shown that TLR4 is particularly associated with sepsis, and TLR4-deficient mice exhibit reduced responsiveness in the face of LPS from Gram-negative bacteria." (PMID 39720715, 2024). "TLR4, a receptor that mediates endotoxic shock and cytokine storms associated with sepsis, has been a particular focus of interest." (PMID 39056754, 2024). "The presence of a specific IRAK-1 variant haplotype, a crucial protein in the TLR2 and TLR4 pathway, is linked to increased nuclear translocation of NF-κB, contributing to a worse prognostic clinical presentation in sepsis." (PMID 38835761, 2024). "In the present study, we have demonstrated that eCIRP enhanced cytotoxicity through GrB and Prf production in CD4CD8αα IELs via TLR4 and caused intestinal epithelial cell death in sepsis." (PMID 38302880, 2024). "The role of the inflammatory response in sepsis-associated AKI points strongly towards TLR4 as a potential mediator in the development of sepsis-associated AKI." (PMID 36674930, 2023).
Sepsis (continued). "TLR4 deficiency or antibody blockade has been shown to be beneficial and can effectively protect animals from sepsis-induced shock and high mortality." (PMID 38114466, 2023). "TLR4 expression in the thick ascending limb is increased in response to sepsis and I/R injury, and this segment has been implicated in mediating inflammatory renal injury during these conditions." (PMID 36674930, 2023). "Our findings support the notion that Sulforaphane has significant anti-inflammatory, anti-oxidative, and anti-apoptotic effects because of its strong inhibitory effect on TLR4/NF-κB signaling pathways, which reduces the heart damage caused by sepsis." (PMID 37900081, 2023). "The interaction between LPS and both systemic and renal TLR4 has been reported in sepsis-associated AKI." (PMID 36674930, 2023). "In recent years, a growing number of studies have found that the TLR4/NF-B signaling pathway is involved in the pathogenic mechanisms of sepsis." (PMID 37650558, 2023). "It has been suggested that TLR4 mediates the hyperactivation of ER stress, leading to Paneth cell loss and dysfunction during intestinal barrier impairment of sepsis." (PMID 38001795, 2023). "Aging leads to elevated baseline TNF-α production by circulating leukocytes and impaired responses to TLR2 and TLR4 agonists, potentially rendering older adults more susceptible to sepsis." (PMID 38001481, 2023). "Pharmacological inhibition or genetic deletion of TLR4 in pre-clinical sepsis models has been associated with reduced glomerular endothelial swelling and vascular permeability, respectively." (PMID 36674930, 2023). "Among the diseases caused by the abnormal activation of TLR4, sepsis is the most dangerous, because it is a life-threatening acute inflammatory condition of the system for which there is still a lack of specific pharmacological treatment." (PMID 37700349, 2023). "The current study aimed to investigate the association of genetic polymorphisms of the TLR2 and TLR4 with the risk of developing sepsis with both a pilot study and in silico tools." (PMID 36142893, 2022). "The development of the Boolean network model in this study was guided by including key biological processes previously identified as key consensus mechanisms associated with TLR4-activation and early sepsis." (PMID 36261775, 2022). "A Boolean network associated with early phase TLR4-mediated sepsis was informed by data extracted from 108 publications." (PMID 36261775, 2022). "Another study also described an association between this SNP and the risk of both sepsis and pneumonia; the same associations were described for the Thr399Ile TLR4 polymorphism whereas the TLR2 polymorphism Arg753Gln was only associated with pneumonia." (PMID 35163998, 2022). "A Boolean network of regulatory relationships was developed for key immune components associated with sepsis pathogenesis after TLR4 activation." (PMID 36261775, 2022). "Additional studies revealed that LIGHT promotes sepsis-associated kidney injury by enhancing the TLR4-MyD88-NF-κB signaling pathway." (PMID 36163116, 2022). "In LPS-induced sepsis, activation of TLR4 causes downstream NF-κB and MAPKs pathways to be activated in a MyD88-dependent manner, thereby enhancing pro-inflammatory cytokines including TNF-α and IL-6." (PMID 36402943, 2022). "LPS is an agonist of Toll-like receptor-4 (TLR-4) that induces proinflammatory signaling cascades causing acute sepsis or chronic inflammatory disorders." (PMID 35054997, 2022). "TLR4 activation promotes release of pro-inflammatory cytokines and infiltration of neutrophils, thereby exacerbating cardiac damage caused by severe sepsis." (PMID 36619743, 2022). "LPS, as an important pathogenic factor in sepsis, has been shown to induce autophagy through toll-like receptor 4 (TLR4) dependent pathway." (PMID 35572571, 2022).
Sepsis (continued). "A novel Boolean network model was developed, which leveraged prior knowledge of immune response-related processes for the TLR4-mediated host response associated with early phase sepsis." (PMID 36261775, 2022). "Many studies have shown that the inflammatory response induced by the TLR4 pathway plays an important role in myocardial injury caused by sepsis." (PMID 35891967, 2022). "In this study, we aimed to investigate the possible role of TLR2 and TLR4 polymorphisms in affecting sepsis susceptibility and survival in critically ill patients in the Egyptian population using both in silico analysis and experimental methods." (PMID 36142893, 2022). "In human sepsis, levels of histones are significantly increased, and consistent with experimental murine models, appear to cause cellular injury in a TLR4-dependent manner." (PMID 35961978, 2022). "In this study, we found that LPA3 deficiency promoted the LPS-induced elevation of CD14 expression, caused an up-regulation of TLR4 signaling in monocytes, and aggravated sepsis injury." (PMID 35464399, 2022). "TLR4/NF-κB signaling pathway is one of the most important mechanisms leading to sepsis associated AKI." (PMID 36263441, 2022). "The results of other studies indicated that sepsis-associated cardiac dysfunction was also mediated by mechanisms other than TLR4." (PMID 35160068, 2022). "From these results, we can draw a conclusion that TLR4 mutation can mitigate CD38 deficiency which aggravates liver injury in sepsis by GSDMD-mediated pyroptosis." (PMID 33860064, 2021). "Previously, it was suggested that sepsis was closely associated with hematopoietic stem cell exhaustion and hematopoietic cell lineage, which was processed through a Toll-like receptor 4 (TLR4)-related mechanism." (PMID 33748037, 2021). "There is evidence that inhibition of the TLR4/MyD88 signaling pathway ameliorates sepsis-associated ARDS in rats by regulating macrophage activation." (PMID 33723330, 2021). "The downstream reaction caused by the combination of TLR4 and LPS is one of the classic pathways of sepsis." (PMID 33816356, 2021). "HMGB1, a danger-associated molecular pattern (DAMP) previously associated with sepsis and shown to activate TLR4 signaling, was released into serum within minutes after the burn, resulting in an increase in TLR4-mediated proinflammatory signaling." (PMID 34152806, 2021). "The only set shared by severe COVID-19, influenza-associated ALI/ARDS and sepsis is that comprised of TLR4, TLR7 and NLRP3." (PMID 33672738, 2021). "In contrast, sepsis patients show decreased TLR4 expression on monocytes that has been associated with worse outcomes and mortality." (PMID 33451043, 2021). "Pharmacological inhibition or genetic deletion of TLR4 in pre-clinical sepsis models was associated with reduced glomerular endothelial swelling and vascular permeability, respectively." (PMID 33467524, 2021). "In this study, we investigated the impact of TLR2 and TLR4 SNPs on susceptibility of AML patients towards developing sepsis, pneumonia and fever during severe neutropenia following intensive chemotherapy as well as its impact on the patient’s outcome." (PMID 33247673, 2020). "In AML patients TLR2 Arg753Gln gene polymorphism is associated with high susceptibility to sepsis and TLR4 (Asp299Gly and Thr399Ile) gene polymorphism is associated with high susceptibility for both pneumonia; and sepsis." (PMID 33247673, 2020). "Our study is the first to show that sesamin can improve sepsis pathophysiology though the TLR4-associated signalling pathway." (PMID 32893702, 2020). "Scavenger receptor CD36 and innate immune receptor TLR4 also recognize Pathogen Associated Molecular Pattern molecules (PAMPs) such as LPS and play important roles in sepsis." (PMID 33362762, 2020). "The soluble form of biglycan initiates and perpetuates the inflammatory response by activating TLR2 and TLR4, and biglycan-deficient mice are less susceptible to death caused by TLR2- or TLR4-dependent sepsis." (PMID 32194548, 2020).